KCNQ1 (potassium voltage-gated channel subfamily Q member 1)
Diseases named in the same sentence as KCNQ1 in open-access papers (continued):
Sharing a sentence is not in itself a finding about the gene and the disease.
long QT syndrome type 1 (39 papers, 2006 to 2025). "These variants included a KCNQ1 variant (c.914G > T, p.Trp305Leu) associated with Long QT syndrome 1 (proband 87), and an MEFV variant (c.2082G > A, p.Met694Ile) associated with Familial Mediterranean fever, autosomal dominant (proband 113)." (PMID 40388540, 2025). "Of these, mutations in the KCNQ1 gene are most common, leading to malfunction of potassium ion channels in the myocardium and a diagnosis of Type 1 Long QT Syndrome (LQT1)." (PMID 40176271, 2025). "It was also shown that allele-specific shRNAs reduced the incidence of arrhythmic events in hiPSC-CMs in the case of a pathogenic (heterozygous) long QT syndrome type 1 mutation in KCNQ1." (PMID 39769116, 2024). "A recent preclinical study demonstrated the effectiveness of dual-component suppression-and-replacement (SupRep) KCNQ1 gene therapy in type 1 long QT syndrome, targeting the molecular cause of the disease." (PMID 38790576, 2024). "Loss-of-function mutations in KCNQ1 cause long QT syndrome type 1 (LQT1) due to an increase in the APD that is exacerbated in exercise, thereby elevating the risk of ventricular tachycardias (torsade de pointes) and sudden cardiac death." (PMID 37650513, 2023). "This ICR is located within an intron of an oppositely transcribed protein-coding gene called Kcnq1, which is important for heart function and whose mutation in humans can cause type 1 long QT syndrome (LQT1, OMIM 192500)." (PMID 37686455, 2023). "Rare variants in the KCNQ1 gene are found in the healthy population to a much greater extent than the prevalence of Long QT Syndrome type 1 (LQTS1)." (PMID 37897496, 2023). "For example, NC P/LPs in KCNQ1, associated with type 1 long QT syndrome, affected 6 European individuals and 1 individual in East Asian or South Asian in the TCGA cohort." (PMID 34503567, 2021). "Loss-of-function (LoF) mutations in KCNQ1, encoding the voltage-gated K+ channel Kv7.1, lead to long QT syndrome 1 (LQT1)." (PMID 34112814, 2021). "Independent of the sex of the transmitting parent, the deletion of the first 12 exons of the KCNQ1 gene predisposes for Long QT 1 syndrome." (PMID 33541417, 2021). "Genetic testing diagnosed the mother and two daughters as type 1 long QT syndrome with KCNQ1 A341V mutation (c.1022C>T)." (PMID 30956674, 2019). "Distributions (mean ± SD) of birth length [in standard deviation scores (SDS)] and birth weight in patients with long QT syndrome 1 due to paternally or maternally inherited KCNQ1 mutations." (PMID 29740400, 2018). "Mutations in KCNQ1 are associated with long QT syndrome type 1 (LQT1), a potentially lethal hereditary arrhythmia." (PMID 29367580, 2018). "We evaluated endocrine features, birth size, and subsequent somatic growth of patients with long QT syndrome 1 (LQT1) due to loss-of-function mutations in KCNQ1." (PMID 29740400, 2018). "Several genetic mutations have been associated to long QT syndrome and one of the most common is the mutation on the KCNQ1 gene leading to long QT syndrome type 1 (LQT1)." (PMID 24705789, 2014). "Variants in the 3′ untranslated region (3′UTR) of the KCNQ1 gene reportedly modify disease severity in individuals with type 1 long QT syndrome resulting from KCNQ1 gene mutations." (PMID 23820649, 2013). "Loss-of-function mutations in KCNQ1 that perturb channel trafficking cause LQT1 (Long QT Syndrome type 1) and may also lead to deafness." (PMID 40593673, 2025). "Loss-of-function of IKs by KCNQ1 variants causes type-1 long QT syndrome (LQTS)." (PMID 39100276, 2024). "Long-QT syndrome type 1 (LQT1) is caused by mutations in KCNQ1." (PMID 35409410, 2022). "Loss-of-function mutations in KCNQ1 cause long QT syndrome type 1 (LQT1), exercise-induced sudden cardiac death, and deafness." (PMID 40593673, 2025). "The study assesses complexity of the cardiac control directed to the sinus node and to ventricles in long QT syndrome type 1 (LQT1) patients with KCNQ1-A341V mutation." (PMID 24705789, 2014).
long QT syndrome type 1 (continued). "Pathogenic mutations in KCNQ1, KCNH2, and SCN5A cause long-QT syndrome types 1, 2, and 3 (LQT1, LQT2, and LQT3), respectively, and together account for 97% of patients with genetically confirmed LQTS." (PMID 35409410, 2022). "So far, such risk stratification has been applied to SCN5A, KCNQ1, and KCNH2 gene variants associated with Brugada syndrome and long QT syndrome types 1 and 2, respectively, but risk stratification of HCN4 gene variants related to sick sinus syndrome has not yet been performed." (PMID 37760888, 2023). "Rather than generating mutated iPSC-CMs from LQTS patients, the ion channel genes KCNQ1 and KCNH2 with dominant negative mutations causing long-QT syndrome types 1 and 2, respectively, were stably integrated into a safe harbor AAVS1 locus using zinc finger nuclease technology." (PMID 33023024, 2020). "They had already applied this SupRep technique to hiPSC-CMs exhibiting an AP prolongation due a reduced IKs as a result of a loss-of-function mutation in the KCNQ1 gene associated with long QT syndrome type 1 and demonstrated that it could substantially, but not fully, reduce the AP prolongation." (PMID 39769116, 2024).
Obesity (33 papers, 2011 to 2025). Accumulation of substantial excess body fat. "On the other hand, genetic variants in KCNQ1, primarily known for its role in cardiac electrical activity, have been associated with obesity, type 2 diabetes (T2D), and stroke." (PMID 41007833, 2025). "KCNQ1 is an obesity susceptibility gene that shows differentially methylated CpG sites between obese and lean women." (PMID 37587247, 2023). "Further analysis identified obesity-induced changes in the KCNQ1 methylation level related to stroke risk." (PMID 35743317, 2022). "Meta-analysis of GWAS in East Asian ancestry populations identified BMI-associated loci near the KCNQ1, indicating the genetic basis of obesity was relevant to this gene." (PMID 32016123, 2020). "Previous studies conducted in Chinese population revealed that KCNQ1 was associated with obesity in Chinese T2DM patients." (PMID 32016123, 2020). "We also investigated the association of KCNQ1 variant with quantitative traits associated with obesity and glucose homeostasis in the study cohort." (PMID 28083030, 2016). "Other studies have indicated that KCNQ1 is associated with obesity and triglyceride levels in Chinese Han populations." (PMID 26678516, 2015). "This aligns with our previous research, which suggested a link between KCNQ1 methylation and obesity and metabolic health." (PMID 41007833, 2025). "The candidate genes were fat mass and obesity-associated (FTO), KCNJ11, potassium voltage-gated channel subfamily Q member 1 (KCNQ1), PDK4, PDX-1, paternally expressed gene-3 (PEG3), PPARG, and stearoyl-coenzyme A desaturase-1 (SCD1)." (PMID 32653024, 2020). "We used our bungarotoxin-binding assay (BBS) developed for KCNQ1 subunits, to test the impact of FFAs elevated in obesity on IK channel subunits." (PMID 31607952, 2019). "KCNQ1 and RPTOR, which showed differences between lean and obese women at many methylated sites, have both been linked to obesity in earlier studies." (PMID 30397228, 2018). "Differential methylation is found within genes associated with obesity, epigenetic regulation and development, such as CETP, FOXP2, HDAC4, DNMT3B, KCNQ1 and HOX clusters." (PMID 25651499, 2015). "Inherited obesity and polygenic obesity (stemming from multiple and synergistic polymorphisms) are thought to involve brain, signaling, and nervous system genes such as NTRK2, KCNQ1, MRAP2, and ADCY3 that regulate satiety and thermo-caloric energy balance." (PMID 36143948, 2022). "Differential methylation was found in genes associated with obesity, epigenetic regulation and development, such as cholesteryl ester transfer protein (CETP), forkhead box P2 (FOXP2), HDAC4, DNMT3B, potassium voltage-gated channel subfamily Q member 1 (KCNQ1) and homeobox (HOX) clusters." (PMID 36397166, 2022). "After correction for multiple testing, these authors identified 1649 CpG sites and 853 genes, including TCF7L2, fat mass and obesity-associated (FTO) and potassium voltage-gated channel subfamily Q member 1 (KCNQ1), with differential DNA methylation in T2D islets." (PMID 34769081, 2021). "Besides FTO polymorphisms, KCNJ11 rs5219, KCNQ1 rs2237892, and TCF7L2 rs7901695 variations have previously been linked to obesity in patients with T2DM." (PMID 34442333, 2021). "Overall, these studies report that adherence to a Mediterranean Diet and/or calorie restriction were associated with decreased DNA methylation in obesity-related genes such as PDK4, KCNQ1, WT1, SH2B1, FTO, BDNF, and PPARGC1A or inflammatory genes such as TNF-α." (PMID 31506096, 2019). "In contrast, SNPs near KCNQ1 and in FTO were associated with obese T2D and mediated via obesity." (PMID 27281091, 2016). "Both TCF7L2 and KCNQ1 have been shown to play essential roles in beta cell survival and function, and they have been suggested to be involved in the modulation of insulin sensitivity and obesity." (PMID 23990951, 2013).
Obesity (continued). "We investigated the association of KCNQ1 variants with quantitative traits associated with obesity and glucose homeostasis including only non-diabetic individuals." (PMID 21261977, 2011). "Our study showed that several risk variants for obesity or metabolic diseases (FTO rs1121980, KCNQ1 rs163182, MC4R rs12970134, and PROX1 rs340841) were also associated with GDM, giving further evidence that GDM and obesity/metabolic diseases may share a similar genetic background." (PMID 32390949, 2020). "Interestingly, the adult obesity-related locus KCNQ1-rs2237892 which was not replicated the association with childhood obesity in our study yield significant association with HDL-C (P = 3.7×10−4) levels independent of BMI." (PMID 29212175, 2017). "In addition, despite our study being sufficiently powered, we failed to confirm the association with obesity for three novel identified adult BMI loci from East ancestry (KCNQ1-rs2237892, PAX6-rs652722 and GP2-rs12597579) in Chinese children." (PMID 29212175, 2017). "Several of the observed DMCs were located in genes related to T2D or obesity, such as ALOX12, PAMR1, and GNAS in WB; IRS1, LEP, and ADIPOQ in SAT; LCAT, FOXA2, KCNQ1, and GCKR in VAT; and PKD4, HNF4A, XBP1, and PON1 in LT." (PMID 29466957, 2018). "Unfortunately, almost all the studies included in current meta-analysis did not explore the interaction between KCNQ1 genotype and obesity." (PMID 23133642, 2012).
long QT syndrome 1 (30 papers, 2012 to 2025). "Loss-of-function variants in KCNQ1 are the primary cause of congenital Long QT Syndrome (LQTS), characterized by QT prolongation and increased risk of fatal arrhythmias." (PMID 41445606, 2025). "Autosomal dominant loss-of-function variants in KCNQ1 result in the LQT syndrome called Romano-Ward syndrome (RWS), while autosomal recessive variants affecting function, lead to Jervell and Lange-Nielsen syndrome (JLNS), associated with deafness." (PMID 36674868, 2023). "Numerous variations in KCNQ1 have been identified to be associated with either LQTS (Romano-Ward syndrome) or JLNS." (PMID 37568094, 2023). "Our study widens the spectrum of novel disease-associated KCNQ1 variants, providing an important or necessary step towards a sound interpretation of the pathogenicity of variants identified in Romano-Ward Syndrome." (PMID 36674868, 2023). "We recently reported the case of a child with normal hearing who suffered sudden death, found to be compound heterozygous for KCNQ1 mutations (P535T/A300T), suggesting recessive Romano-Ward syndrome." (PMID 33693037, 2021). "Next Generation Sequencing has identified many KCNQ1 genetic variants associated with type 1 long QT or Romano-Ward syndrome, most frequently inherited in an autosomal dominant fashion, although recessive forms have been reported." (PMID 33693037, 2021). "Patients with mutations on both KCNQ1 alleles, a prolonged QT interval and normal hearing suffer from recessive Romano-Ward syndrome and are considered a high-risk subgroup." (PMID 33693037, 2021). "Mutations in KCNQ1 gene were associated with congenital Long QT Syndrome (LQTS) and some variants were associated with diabetes." (PMID 30123371, 2018). "Variants of KCNQ1 cause a variety of disorders including hereditary long QT syndrome (Romano-Ward syndrome)." (PMID 26789123, 2016). "KCNQ1 mutations are associated with cardiac diseases such as hereditary long QT syndrome and familial atrial fibrillation." (PMID 26678516, 2015). "In summary, the genetic and molecular analyses of this work have confirmed the index patient’s diagnosis of Jervell and Lange-Nielsen syndrome 1 (JLNS1) by the identification of biallelic variants in the KCNQ1 gene, p.R259L and a previously undescribed intronic variant c.1686−9 T > C." (PMID 33664273, 2021). "Similarly, other KCNQ1 genetic mutations within this region have been associated with recessive Romano-Ward syndrome." (PMID 33693037, 2021). "Mutations in KCNQ1 and KCNE1 leads to malfunctioning of the channel and thus cause Romano-Ward syndrome and Jervell and Lange-Nielsen syndrome." (PMID 34722422, 2021). "Additionally, there is the autosomal dominant form of LQTS1, also denoted as Romano-Ward Syndrome (RWS), usually a clinically milder form with genetically heterozygous missense, nonsense, exon skipping, and frameshift variants affecting KCNQ1 channel function." (PMID 36674868, 2023). "Regarding the etiology of channelopathies such as the Congenital Long QT Syndromes itself, 75% of LQTS cases are linked to mutations in genes encoding for voltage-gated potassium channel subunits (KCNQ1, KCNH2, KCNE1, KCNE2), or for voltage-gated sodium channel SCN5A." (PMID 36421220, 2022). "Loss of function (LOF) mutations of voltage sensitive K+ channel proteins hERG (Kv11.1) and KCNQ1 (Kv7.1) account for the majority of instances of congenital Long QT Syndrome (cLQTS) with the dominant molecular phenotype being a mistrafficking one resulting from protein misfolding." (PMID 36339618, 2022). "Because an undiagnosed child with sudden death was found to be compound heterozygous for KCNQ1 mutations (P535T/A300T), we functionally characterized the IKs of HEK293 cells expressing both mutations to establish whether she was affected with a form of recessive Romano-Ward syndrome." (PMID 33693037, 2021).
short QT syndrome (30 papers, 2008 to 2025). A genetic disease of the electrical system of the heart that consists of a constellation of signs and symptoms, consisting of a short QT interval on an EKG (< 300 ms) that does not significantly change with heart rate, tall and peaked T waves, and a structurally normal heart. "Mutations in KCNQ1, which encodes for KvLQT1 a component of IKs can lead to Short QT Syndrome (SQTS) due to a gain of function in IKs." (PMID 41351260, 2025). "For example, it is known that both long and short QT syndromes arising from loss and gain of function mutations, respectively, in KCNQ1 can result in sudden cardiac death in afflicted families." (PMID 31423533, 2020). "Loss-of-function mutations in KCNQ1 are linked to an increase in AP duration associated with long QT-syndrome type I, whereas gain-of-function mutations in KCNQ1 are associated with short QT-syndrome (SQT2) and familial AF." (PMID 24600393, 2014). "Conversely, KCNQ1 gain of function mutations result in hastening of the cardiac action potential repolarization causing Short QT syndrome and atrial fibrillation." (PMID 21915266, 2011). "Although KCNQ1 gain-of-function mutations have been described in short QT syndrome, to our knowledge there is only one report of a heterozygous KCNQ1 mutation also located within D5 (p.A399S) in a young man with ER and sudden cardiac death, without establishing the causal role of the mutation." (PMID 38256028, 2024). "Short QT syndrome due to these mutation, including KCNQ1 S140G mutation, is an inherited, rare, potential lethal disease characterized by ventricular repolarization alternans, predisposing to atrial fibrillation, syncope, and high incidence of sudden cardiac death." (PMID 30108508, 2018). "In addition to LQTS and JLNS, there is some emerging evidence that certain variants in KCNQ1 also cause Short QT Syndrome (SQTS)." (PMID 27446933, 2016). "Nevertheless, the remainder of this review will principally focus on links between KCNH2/hERG, KCNQ1 and KCNJ2 and short QT syndrome as these potassium channel genes can be causally linked to SQTS with a high degree of confidence." (PMID 37122211, 2023). "There have been more than 600 mutations described in KCNQ1, which are associated with either LQT1 or much less frequently short-QT syndrome type 2 (SQT2)." (PMID 35409410, 2022). "So far, gain-of-function mutations in KCNQ1, KCNH2, and KCNJ2 have been associated only with rare cases of short QT syndrome (SQTS) and/or AF." (PMID 24972929, 2014). "However, among three definite LQTS genes, KCNQ1 and KCNH2 are also reported as causative genes for the short-QT syndrome." (PMID 36480497, 2022). "While a majority of the known KCNQ1 disease variants exhibit channel LOF that results in LQTS arrhythmia, a smaller set of variants result in what is thought to be aberrant GOF, resulting in short QT syndrome or familial AF." (PMID 33600800, 2021).